ALOX15 (arachidonate 15-lipoxygenase)
Diseases named in the same sentence as ALOX15 in open-access papers (continued):
Sharing a sentence is not in itself a finding about the gene and the disease.
infection (13 papers, 2016 to 2025). The state of being infected such as from the introduction of a foreign agent such as serum, vaccine, antigenic substance or organism. "Lung exposure to A. fumigatus resulted in rapid mortality in 12/15-LOX-deficient mice (Alox15−/−), with nearly a third of the mice succumbing to infection within 36 h and only 20% of mice surviving by 72 h." (PMID 32102903, 2020). "In contrast, Alox15−/− ALI monolayers failed to trigger significant PMN transmigration during infection by either WT or PLY-deficient Sp (“Alox15−/−”)." (PMID 39120139, 2024). "In contrast, similar to our 6 h infection data, we observed that naive Alox15−/− mice (at 6–8 wk old, which were employed for all studies in the current body of work) demonstrated lower levels of myelocytes (stage 3), metamyelocytes (stage 4), and mature neutrophils (stage 5) in the bone marrow." (PMID 32102903, 2020). "As an answer to these questions, the infection of mice deficient for Toll-like receptor 2 (TLR2), TLR4, IL-10, arachidonate 5-lipoxygenase (ALOX5), or arachidonate 15-lipoxygenase (ALOX15) with the M. tuberculosis Δnrp strain showed the same phenotype as WT mice." (PMID 30381350, 2018). "Because infection with the helminth Taenia crassiceps was previously shown to increase Alox15 expression in peritoneal macrophages in response to interleukin (IL)-4 signaling, we hypothesized that Hpb may similarly promote 12/15-LOX oxylipin production through this pathway." (PMID 40490052, 2025). "RSV Long strain induces mRNA expression of Alox15, the first enzyme in the conversion of DHA to PCTR1 or PD1, at days 1-4 post infection in mouse lungs." (PMID 34489955, 2021). "Among them, 25 genes, such as arachidonate 15-lipoxygenase (ALOX15), collagen, type VI, α5 (COL6A5), and serglycin (SRGN), were significantly upregulated while the expression of transthyretin (TTC) was repressed by infection." (PMID 27197554, 2016).
metabolic disease (10 papers, 2016 to 2025). A congenital disorder (due to inherited enzyme abnormality) or acquired (due to failure of a metabolically important organ) disorder resulting from an abnormal metabolic process. "Alterations in ALOX15 regulation have been observed in various cardiovascular, renal, neurological and metabolic disorders." (PMID 38900131, 2024). "To explore the putative role of ALOX15 in adipogenesis and in the pathogenesis of metabolic diseases, we recently generated a transgenic mouse line, in which expression of human ALOX15 was controlled by the aP2 promoter." (PMID 37498393, 2023). "Arachidonic acid lipoxygenases (ALOX) have been implicated in the pathogenesis of inflammatory, hyperproliferative, neurodegenerative, and metabolic diseases, but the physiological function of ALOX15 still remains a matter of discussion." (PMID 36902243, 2023). "More researches are needed to determine whether the regulatory role of ALOX15 in DM is specific to DM or applies to other related metabolic diseases." (PMID 37849828, 2023). "ALOX15 is a member of the lipoxygenase family, which plays an important role in polyunsaturated fatty acid metabolism, indicating that metabolic disorders may have occurred in PCOS granulosa cells." (PMID 35237237, 2022).
neurodegenerative disease (6 papers, 2016 to 2024). A disorder of the central nervous system characterized by gradual and progressive loss of neural tissue and neurologic function. "In conclusion, the newly identified lead compounds offer potential for the development of ALOX15 inhibitors for treating inflammation-mediated injury and degenerative diseases associated with ferroptosis." (PMID 38213304, 2024). "Thus, the inhibition of ALOX family enzymes, particularly ALOX15, is essential for the treatment of injury and degenerative diseases triggered by ferroptosis." (PMID 36422570, 2022). "Thus, ALOX15 has become a popular target in the study of many diseases, including tumors and degenerative diseases." (PMID 36422570, 2022). "The distinct patterns of relative distribution and localization as elucidated by this investigation may provide insight into the roles of Alox15 in synaptic plasticity and neurodegenerative diseases." (PMID 28181190, 2018).
inflammation (5 papers, 2016 to 2024). Aberrant reaction of the microcirculation characterized by movement of fluid and leukocytes from the blood into extravascular tissues. "IL-13 induces Arachidonic Acid 15-Lipoxygenase (ALOX15) expression, an enzyme oxidizing polyunsaturated fatty acids, and causes eosinophil-mediated airway inflammation." (PMID 35887565, 2022). "15-Lipoxygenase-1 (ALOX15) has been implicated in vascular inflammation and disease." (PMID 27594770, 2016). "Thus, ALOX-15 pathway plays an important role in underlying pathogenesis of airway inflammation Arachidonic acid 15-lipoxygenase (ALOX-15) gene, located on chromosome 17p13.3, controls transcriptional activity and hence, function of lipoxins Eleven gene variations were detected." (PMID 38685084, 2024).
cardiovascular disease (4 papers, 2012 to 2026). "Sequence variations in the promoter of the reticulocyte-type 15-lipoxygenase gene (ALOX15) has been associated with cardiovascular disease." (PMID 22879973, 2012). "ALOX15, a member of lipoxygenase family, has been implicated in the pathogenesis of cardiovascular disease through its effects on atherogenesis, vascular function and remodeling." (PMID 22879973, 2012). "Although ALOX15 has been implicated in cardiovascular disease genesis, it has not been previously associated with RHD." (PMID 37018379, 2023).
kidney disease (4 papers, 2021 to 2024). "The research reported that in a mouse model of T1DM kidney disease, the mRNA and protein levels of Alox15 are positively correlated with the expression level of fibronectin, and the urinary excretion rate of 12S-HETE is increased." (PMID 37849828, 2023). "In addition, in obese nephropathy, ALOX15 also tends to be highly expressed, and the growth in its expression level is related to the activation of P38/MAPK as well as ERKl/2 pathways." (PMID 37849828, 2023). "In addition, in kidney disease, compared with wild-type animals, renal inflammation, fibrosis and macrophages infiltration were significantly reduced after UUO treatment in Alox15 knockout mice." (PMID 37849828, 2023).
neurological disorders (3 papers, 2023 to 2024). "Mammalian ALOX15 orthologs have been implicated in cell differentiation and in the pathogenesis of inflammatory, hyperproliferative metabolic and neurological diseases but the precise role of the enzyme in inflammation is far from clear." (PMID 37498393, 2023).
vascular disorder (1 paper, 2023). A general term used to describe any disease affecting blood vessels]. "There are six known functional LOX genes in humans (ALOX5, ALOX12, ALOX12B, ALOX15, ALOX15B, ALOXE3), but only three of them, 5-LOX, 12-LOX (platelet-type), and 15-LOX (reticulocyte-type), appear to be important for vascular disorders." (PMID 36675152, 2023).
ALOX15 also shares sentences with these, for which no sentence is quoted: allergic disease (4 papers); allergic rhinitis (3); brain trauma (3); cervical cancer (3); chronic obstructive pulmonary disease (3); endothelial dysfunction (3); rheumatoid arthritis (3); viral infection (3); Allergy (2); Anxiety (2); cerebrovascular diseases (2); colon adenocarcinoma (2); colon adenoma (2); glioblastoma (2); hepatocellular carcinoma (2); osteoarthritis (2); rhinitis (2); systemic sclerosis (2); acute kidney injury (1); acute pancreatitis (1); Airway obstruction (1); animal disease (1); aortic aneurysm (1); arteriosclerosis (1); brain tumor (1); bronchospasm (1); cancers of the head and neck (1); choroid plexus papilloma (1); chronic sinusitis (1); clear cell renal cell carcinoma (1).
A further 41 diseases each share a sentence with ALOX15 in 1 paper.